CRP (C-reactive protein)
Diseases named in the same sentence as CRP in open-access papers (continued):
Sharing a sentence is not in itself a finding about the gene and the disease.
Hypertension (continued). "Angiotensin converting enzyme (ACE) inhibitors have shown beneficial effects on endothelial function in patients with hypertension and other cardiovascular diseases, however there are few studies evaluating the effect of treatment with this class on the reduction of C-reactive protein (CRP) levels." (PMID 31337127, 2019). "Higher CRP levels and arterial hypertension were also more prevalent in this subset of patients." (PMID 30952206, 2019). "Another justification behind the lower rate of high serum hs-CRP level in the present study may be the lower rates of hypertension, cigarette smoking, and hyperglycemia among study participants." (PMID 31814938, 2019). "So this study is designed to determine the possible inflammatory role of resistin by observing its association with other documented inflammatory biomarkers such as TLC & CRP in cases of variable degrees of cardiovascular disease i.e. hypertension, angina pectoris and myocardial infarction." (PMID 31258568, 2019). "Regarding ACEIs, clinical trials have shown beneficial effects on endothelial function in patients with hypertension and other cardiovascular diseases, however, there are few studies evaluating the effect of treatment with this class on the reduction of CRP levels." (PMID 31337127, 2019). "PS, MS, hypertension, and aging share in common an increase in C-reactive protein (CRP), which may implicate an extra burden for increased cardiovascular risk." (PMID 31938651, 2019). "A multiple linear regression analysis with htTKV as dependent variable, including hypertension, CRP, eGFR, age, time since diagnosis, VDR, and 25(OH)D adjusted for season of the year showed that only the first three parameters were independent predictors of the former." (PMID 31179282, 2019). "Indeed, COX-2 inhibition, by means of celecoxib, reduces CRP levels in patients with both severe CAD and arterial hypertension associating with an improved endothelial function." (PMID 30935055, 2019). "We explored four outcomes in relation to sociodemographic and behavioral determinants: 1) hypertension, 2) elevated high-sensitivity c-reactive protein (hs-CRP), and 3) central obesity, as these are critical metabolic determinants in the progression to cardiovascular disease, and 4) type 2 diabetes." (PMID 31469876, 2019). "Similarly, whereas in subgroup analyses the positive association between E-Selectin and T2D was present in almost all strata, it was slightly weaker in studies with adjustment for CRP, hypertension, and glucose." (PMID 31783601, 2019). "As such, the present study provides the strongest evidence regarding the involvement (or lack thereof) of CRP, sICAM-1, sVCAM-1 and sE-selectin in the pathogenesis of elevated pulse pressure and of hypertension, over the course of disease in individuals with type 1 diabetes." (PMID 29101422, 2018). "A subsequent study from the same group detected a 4-fold higher risk for carotid artery plaque and/or coronary artery calcification in SLE patients with depression, when age, waist to hip ratio, lower education level, arterial hypertension, and CRP values were taken into account." (PMID 29971022, 2018). "Similarly, the key inflammatory marker, C-reactive protein (CRP), has been linked to insulin resistance, hypertension, development of type 2 diabetes and metabolic syndrome." (PMID 29772682, 2018). "Adjusting for IL-6 and C-reactive protein as well as hypertension, physical inactivity, and low FEV, led to further marked attenuation of the socioeconomic gradient in frailty, in line with the role of serum C-reactive protein concentration in predicting ADL disability." (PMID 29908857, 2018). "Age (≥ 65 years), female sex, RA duration (≤ 3 years), RA stages III and IV, HAQ (≥ 1.0), serum CRP levels, BMI (> 25), hypertension, NIDDM, serum LDL-C (≥ 140 mg/dl), smoking history, biological DMARD use, NSAID use, and cumulative steroid dose (≥ 5.5 g) were selected as independent variables." (PMID 28884373, 2017).
Hypertension (continued). "On the other end, the higher CRP levels among night-shift workers, remarkably independent of the considered CD risk factors (such as smoking, BMI, and hypertension), suggest that night-shift work is associated with increased systemic inflammation." (PMID 28536575, 2017). "Furthermore, we found that higher CMV IgG titer and CRP levels were an independent risk factor of hypertension progression and hypertensive TOD and that CMV IgG titers were positively correlated with CRP and IL-6 levels." (PMID 28837559, 2017). "The aim of this preliminary study was to compare the relative utility of AHI versus CRP in detecting, cross‐sectionally, the presence and severity of hypertension and hyperglycemia in middle‐aged adults with mild‐to‐moderate (5 ≤ AHI < 30) obstructive sleep apnea." (PMID 28947597, 2017). "Ln (hs-CRP) was independently associated with rMSSD, pNN50, LF power, HF power, SD1, SD2, following adjustments for multiple variables (i.e., age, sex, BMI, presence of hypertension, RA diagnosis and serum haemoglobin concentration)." (PMID 28927867, 2017). "The authors concluded that a history of hypertension in pregnancy is associated with elevated CRP levels later in life, independent of traditional CVD risk factors and BMI." (PMID 28749442, 2017). "Moreover, CRP levels had a significant positive relationship with higher grade of BP and hypertension in all models (model 3 of group 1, P = 0.003; others, P<0.001) and with hypertensive TOD only in models 1 and 2 (model 1, P = 0.048; model 2, P = 0.0135)." (PMID 28837559, 2017). "Similarly, an obese, middle‐aged woman with AHI = 10 has a 15.27% and 8.33% probability of hypertension and hyperglycemia, respectively, if their CRP = 0.5 mg/L; these probabilities increase to 30.24% and 28.43% if their CRP = 3.0 mg/L." (PMID 28947597, 2017). "The office blood pressure, BMI, CRP, Hcy, and angiotensin II levels were significantly higher in the hypertension group than in the control group, whereas the high-density lipoprotein cholesterol (HDL-C) levels were significantly lower in the hypertension group than in the control group." (PMID 28757677, 2017). "We assume that in the study as well as in clinical practice, there is a trend towards more seriously ill patients being hospitalized, shown by the higher proportion of patients with congestive heart failure, high blood pressure and high CRP in the hospital group." (PMID 28880941, 2017). "Conversely, another study involving obese white and black women in South Africa showed high mean (IQR) hs-CRP levels in patients with hypertension (3.50 [2.05–4.95] and 5.50 [3.04–7.95] mg/L, respectively), and both risk factors were related to arterial compliance." (PMID 27166776, 2016). "Taken together, it suggests that CRP and TNF-α may be one of the factors that predisposes individuals to hypertension." (PMID 26989902, 2016). "Although it did not evaluate metabolic phenotypes, a recent work in 100 coronary patients showed that some of the factors used for defining the metabolic phenotypes (such as hypertension, LDL or C-reactive protein) were associated with higher carotid atherosclerotic parameters." (PMID 27064675, 2016). "Studies have shown that CRP can aggravate hypertension via several mechanisms." (PMID 26858795, 2016). "However, after comparing participants and non-participants, we found that non-participants were of older age and had higher baseline levels of hs-CRP, UA, and RHR, which are risk factors for hypertension." (PMID 27434049, 2016).
Hypertension (continued). "It is reported that high-sensitivity CRP induced high blood pressure and progress of blood vessel inflammation, which is related with adhesion molecules, ET-1 and inflammatory cytokine in vascular endothelial of a blood vessel and increased in an initial stage of atherosclerosis." (PMID 26961224, 2016). "There is some evidence that C-reactive protein (CRP), commonly elevated in hypertension, can promote detrimental effects on the vascular wall, inducing endothelial dysfunction and reducing nitric oxide bioavailability, which also operates in tissue coagulation." (PMID 25996882, 2015). "On univariate Cox proportional hazard analyses, both CRP and oxLDL were associated with increased risk for incident hypertension in lone AF patients, both as continuous variables (not presented) and per quartile increase." (PMID 26229238, 2015). "Genome-wide association studies (GWAS) have discovered multiple single-nucleotide polymorphisms (SNPs) associated with inflammatory markers including CRP and different cardiometabolic phenotypes including T2D, coronary artery disease (CAD), lipids and hypertension." (PMID 25768928, 2015). "The association between CRP and LVH would be more significant with the progress of hypertension." (PMID 25793884, 2015). "For example, lower plasma ascorbic acid values relate to higher levels of C-reactive protein, which, in turn, may contribute to hypertension." (PMID 26683190, 2015). "Lower concentration of this mediator in our hypertensive patients despite elevated CRP levels in this group may suggest that this mechanism is impaired in hypertension." (PMID 25951297, 2015). "The prevalence of several other clinical symptoms are correlated with GGT, including hypertension, insulin resistance, artery calcification, and albuminuria, as well as biological markers including lipids, creatine, triglycerides, uric acid, HbA1c, and hs-CRP." (PMID 26543300, 2015). "Simple linear regression analysis showed that age, gender, BMI, SBP, DBP, mean arterial pressure (MAP), pulse pressure (PP), BP classification, alcohol consumption, hypertension, TG, TC, LDL-C, hs-CRP, and CRVE were significantly associated with CRAE (all P≤0.041)." (PMID 25188273, 2014). "We also showed that increased Prx4 levels are associated with some components of the metabolic syndrome (such as hypertension and triglycerols) and with well-established inflammatory markers (such as high sensitivity C-reactive protein [hs-CRP] and procalcitonin)." (PMID 24893865, 2014). "The association of CRP with hypertension in the setting of periodontitis has not been consistent, possibly due to many other factors that can elevate inflammatory markers, or simply hypertension itself is a multifactorial disease." (PMID 24526921, 2014). "Because hypertension is an independent risk factor for heamorrhagic stroke, to further explore the potential association between hs-CRP and heamorrhagic stroke, subgroup analysis was carried out based on hypertension status (yes/no)." (PMID 25191699, 2014). "In humans, many lines of evidence that established essential hypertension as a condition of chronic low-grade inflammatory status also revealed a strict and independent association between CRP, TNF-α, and IL-6 or adhesion of molecules and vascular changes in essential hypertensive patients." (PMID 25143940, 2014). "CRP is a biomarker of systemic inflammation and a risk factor for the development of inflammation-mediated diseases such as CVD, metabolic syndrome, type 2 diabetes and hypertension." (PMID 23977389, 2013). "In the present study, and in agreement with two previous studies, a direct association between the prevalence of hypertension and inflammation (as assessed by C-reactive protein) was not identified." (PMID 24286134, 2013). "CRP levels were higher in patients who fulfilled any single criterion except for hypertension." (PMID 23758640, 2013).
Hypertension (continued). "In particular, the effect of an elevated E/E’ ratio on the presence of carotid atherosclerosis was independent of other CV risk factors, including old age, hypertension, high pulse pressure, hs-CRP level, and the use of statins." (PMID 24192205, 2013). "C-reactive protein (CRP) plays an important role in hypertension and is correlated with OSAS." (PMID 23009224, 2012). "Results of multivariable Cox regression demonstrated non-significance (p = 0.17) for peak versus base subjects in a model adjusted for gender, age, BMI, hypertension, metabolic syndrome, smoking, and levels of apoA-I, apoA-II, apoB, apoE, total cholesterol, CRP, HDL-C, and triglycerides." (PMID 22723940, 2012). "However, in the Caucasian women, cortisol presented a higher likelihood of contribution towards hypertension than in the African women, whereas in the hypertensive African women, CRP seemed to play a larger role." (PMID 22447476, 2012). "In another study on the effects of Carvedilol and Propranolol on oxidative stress in mononuclear and polynuclear cells in patients with hypertension, Carvedilol was reportedly much superior to Propranolol in inhibiting oxidative stress and reducing the level of CRP." (PMID 24757599, 2012). "However, in cohort studies, moderate consumption of alcohol is associated with decreased incidence of hypertension and improved cardiovascular biomarkers such as higher HDL-cholesterol and lower C-reactive protein (CRP)." (PMID 21655140, 2011). "Moreover, although the chefs often had higher CRP-concentrations (40.0%), more office workers suffered from hypertension (37.5%)." (PMID 20307278, 2010). "The systemic inflammatory biomarker C-reactive protein (CRP) when measured in the blood with high sensitivity assay has been reported to be a strong and independent predictor of myocardial infarction, ischemic stroke, type 2 diabetes, and hypertension." (PMID 20482756, 2010). "Furthermore, chefs often had higher CRP-concentrations whereas more office worker suffered from hypertension." (PMID 20307278, 2010). "Hence, patients with hypertension and increased CRP levels may be more burdened with multi-morbidities." (PMID 40137683, 2025). "It further aims to determine the extent to which inflammatory markers—leukocytes, neutrophils, and CRP—correlate with diastolic impairment, and whether this relationship is modulated by the presence of metabolic conditions such as hypertension, type 2 diabetes mellitus, dyslipidemia, or obesity." (PMID 41303851, 2025). "The increased concentration of CRP is also measured in patients with sleep apnea where hypoxia and then reproduced oxidative stress predetermines inflammation in the whole organism and, therefore, worsening of basic illnesses, hypertension, cardiovascular diseases, and metabolic disorders." (PMID 40662069, 2025). "Incidence of C-reactive protein (CRP) >5 mg/L, of metabolic (dysfunction)-associated fatty liver disease (MAFLD; previously called nonalcoholic fatty liver disease), and of arterial hypertension showed a significant progressive increase from NFG to IFG and to DM." (PMID 39196799, 2024). "Indeed, metabolic syndrome, a cluster of cardiometabolic risk factors including chronically elevated c-reactive protein (CRP), dyslipidemia, hypertension, and hyperglycemia, is more common in MDD and psychiatric disorders generally than in the general population." (PMID 39458533, 2024). "Notably, individuals who succumbed to AKI had discernible characteristics: they were often above 65 years of age, had a medical history dominated by arterial hypertension, exhibited elevated white blood cell counts and CRP levels, and faced a grim clinical trajectory characterized by prostration." (PMID 38804444, 2024). "Moreover, CRP can also serve as a predictor for cardiovascular health, and in individuals with normal blood pressure, elevated CRP levels can predict the future development of hypertension." (PMID 39246645, 2024).
Hypertension (continued). "However, the number of patients aged 60 and above, history of hypertension, the number of patients without underlying diseases, C-reactive protein (CRP), and the Lym % showed significant differences (P < 0.05)." (PMID 39184027, 2024). "Moreover, we observed noticeable differences between the groups in age, ICU admission, hypertension, viral encephalitis, consciousness dysfunction, neutrophils, lymphocytes, Fib, TT, D-dimer, Alb, CRP, the initial mRS, the finial mRS, and MRI findings (P < 0.05)." (PMID 36908596, 2023). "Age, sex, BMI, hypertension, smoking, GFR, triglycerides, LDL cholesterol, and HDL cholesterol, fasting glucose, fasting insulin, glycated hemoglobin, newly diagnosed type 2 diabetes per American Diabetes Association 2,010 guidelines, proinsulin, free fatty acids, free glycerol, and CRP." (PMID 37485272, 2023). "In our study, 57.5% of patients had prior hypertension, while the majority of blood pressure parameters registered at night (mean systolic blood pressure and mean pulse pressure) were associated with AHI, as well as with several lipid and inflammatory markers, including triglycerides, CRP, and ESR." (PMID 35784707, 2022). "Early screening and intervention of CRP may delay the progression of hypertension." (PMID 36418968, 2022). "Furthermore, CRP presented significantly elevated values in the hypertension and COPD subgroups." (PMID 35746672, 2022). "Therefore, in this study, we aimed to explore the CRP correlation with hypertension in the elderly." (PMID 36418968, 2022). "One patient (7.7%) presented with arterial hypertension, another patient (7.7%) had febrile temperatures up to 38.7° C. Laboratory results showed elevated leukocytes in nine patients (69.2%) and conspicuous C-reactive protein (CRP) values in all but two patients (84.6%)." (PMID 35715523, 2022). "CRP is a well-known inflammatory biomarker produced by the liver and atherosclerotic plaques and is a clinical marker for different diseases, such as ischemic stroke, coronary artery disease, hypertension, insulin resistance, peripheral artery disease, and metabolic syndrome." (PMID 36614866, 2022). "Elevated-CRP levels and hypertension may be positive factors in the progression of atherosclerosis." (PMID 36262245, 2022). "However, our data suggest that CRP itself does not adequately predict hypertension and should be used in combination with other risk markers (e.g., baseline BP, age, WC, and TG)." (PMID 34925916, 2021). "CRP was related with death risk in patients with hypertension, but not liver diseases." (PMID 33112011, 2021). "In addition to C-reactive protein and IL-6, TNF-α, IL-1β, IL-18, and CCL2 cytokine levels also appear to be increased in hypertension and may confer risk of developing the disease." (PMID 34698811, 2021). "Therefore, it is necessary to continue to study the relationship between CRP and hypertension." (PMID 34925916, 2021). "Multivariate logistic regression identified chronic pulmonary disease (odds ratio (OR) 2.06), hypertension (OR 0.48), unknown infection source (OR 1.82), a hepatobiliary infection source (OR 0.25), C-reactive protein (OR 1.03), and serum lactate level 6 h from shock (OR 1.34)." (PMID 34067038, 2021). "Importantly, this latter study also showed that the association was higher for subjects with hypertension than in normo-tensive individuals, suggesting that the association between D-NEAC and plasma CRP may strengthen under pro-inflammatory conditions." (PMID 32260517, 2020). "Prior reviews have emphasized that the weight loss-related resolution of somatic comorbidities might play a more important role, including Type 2 diabetes (T2D), hypertension, sleep apnea and metabolic inflammation (often measured via C-reactive protein (CRP) levels)." (PMID 33488469, 2020).